MOB3B (MOB kinase activator 3B)
Description:
Modulates LATS1 expression in the Hippo signaling pathway which plays a pivotal role in organ size control and tumor suppression by restricting proliferation and promoting apoptosis.
Synonyms: C9orf35; MOBKL2B; MOB1D; FLJ13204
Tractability: PROTAC: ubiquitination databases record sites on it.
Gene: Protein-coding gene on chromosome 9 (27,325,209 to 27,529,814, reverse strand). Ensembl gene ENSG00000120162.
Subcellular location (Human Protein Atlas): Cytosol; Intermediate filaments
Gene Ontology:
Molecular function: protein binding; protein kinase activator activity
Biological process: regulation of hippo signaling
Genetic constraint (gnomAD): Loss-of-function variants: 7 observed, 19.65 expected, observed/expected ratio (o/e) 0.36, 90% interval 0.2 to 0.67. The upper end of that interval is the gene's LOEUF score, 0.67, which puts it in group 2 of 6, group 1 being the genes least tolerant of losing a copy. Missense variants: 253 observed, 296.39 expected, observed/expected ratio (o/e) 0.85, 90% interval 0.77 to 0.95. Synonymous variants: 111 observed, 106.42 expected, observed/expected ratio (o/e) 1.04, 90% interval 0.89 to 1.22.
Homologues: Orthologues: chimpanzee MOB3B (100% identical), macaque MOB3B (100% identical), pig MOB3B (99% identical), dog MOB3B (99% identical), rat Mob3b (99% identical), mouse Mob3b (98% identical), guinea pig MOB3B (97% identical), tropical clawed frog mob3b (88% identical), Drosophila melanogaster Mob3 (67% identical), Caenorhabditis elegans mob-3 (65% identical). Paralogues in human: MOB3A (81% identical), MOB3C (72% identical), MOB1B (55% identical), MOB1A (53% identical), MOB2 (34% identical), MOB4 (23% identical).
Diseases named in the same sentence as MOB3B in open-access papers:
MOB3B is named in the same sentence as 11 diseases in open-access papers, as found by Europe PMC text mining. Sharing a sentence is not in itself a finding about the gene and the disease. The quoted sentences say what the papers report.
prostate carcinoma (4 papers, 2017 to 2022). A carcinoma that arises from epithelial cells of the prostate gland. "Similarly MOB3B (or MOB1) is a pivotal kinase player in the Hippo tumor suppressor pathway, and mutations in this gene is associated to prostate cancer susceptibility and agressive tumors." (PMID 31568528, 2019). "In this study, we show that prostate cancer-specific hypermethylation of the eight genes AOX1, CCDC181 (C1orf114), GABRE, GAS6, HAPLN3, KLF8, MOB3B, and SLC18A2 can be detected by qMSP with very high sensitivity and specificity in scarce prostate needle biopsy samples taken at the time of diagnosis." (PMID 28084441, 2017).
breast carcinoma (1 paper, 2018). "In prostate, stomach, and breast cancer, DOK6 and MOB3B were reported as putative tumor suppressor genes." (PMID 30454026, 2018).
malignant melanoma (1 paper, 2019). "Similarly, low expression of MOB3B has been associated with malignant melanoma, mantle cell lymphoma, poor outcome of renal cancer and adverse clinicopathological factors in PCa, together suggesting a possible tumor suppressor role for MOB3B." (PMID 30866497, 2019).
tumor (6 papers, 2018 to 2023). "Furthermore, KDM5A was found to downregulate MOB3B expression, consequently augmenting PCa cell proliferation, migration and invasion in vitro and promoting tumor growth in vivo via the miR-495/YTHDF2 axis." (PMID 33087165, 2020). "We carried out xenograft tumor experiments on the nude mice in order to verify the effect of KDM5A on PCa initiation and progression via the miR-495/YTHDF2/MOB3B axis in vivo." (PMID 33087165, 2020). "In summary, our study demonstrates that the overexpression of KDM5A has a tumor-supporting effect on PCa, as it suppresses the YTHDF2-dependent MOB3B expression by binding to miR-495." (PMID 33087165, 2020).
cancer (5 papers, 2005 to 2022). A tumor composed of atypical neoplastic, often pleomorphic cells that invade other tissues. "scMob1 binds Mps1p, a protein kinase essential for spindle pole body duplication and mitotic checkpoint regulation, which in turn plays a role in maintaining genome stability, again providing biological plausibility for loss of MOB3B in cancer." (PMID 16457699, 2005). "Also MOB3B functions in the Hippo signal transduction pathway, and alterations of this gene have been associated with different types of cancer." (PMID 36232302, 2022).
neurodegenerative disease (1 paper, 2024). A disorder of the central nervous system characterized by gradual and progressive loss of neural tissue and neurologic function. "Although there is relatively limited research on the specific role of MOB3B in neurodegenerative diseases, considering its potential role in regulating cell survival signals, MOB3B may play a role in ALS." (PMID 38819224, 2024).
MOB3B also shares sentences with these, for which no sentence is quoted: autoimmune disease (1 paper); immune deficiency (1); mantle cell lymphoma (1); renal carcinoma (1); rheumatoid arthritis (1).